FEN1 (flap structure-specific endonuclease 1)
Diseases named in the same sentence as FEN1 in open-access papers (continued):
Sharing a sentence is not in itself a finding about the gene and the disease.
tumor (95 papers, 2013 to 2026). "FEN1 is a crucial valvular endonuclease involved in DNA repair, and its overexpression has been associated with tumor progression and heightened cell proliferation." (PMID 40612863, 2025). "In some cases, its overexpression is correlated with hypomethylation of the FEN1 promoter and linked to increased tumour grade and aggressiveness." (PMID 35883600, 2022). "FEN1 has been found to have abnormal expression or mutation in a variety of solid tumors, which has promoted the proliferation and migration of tumor cells." (PMID 35883563, 2022). "FEN1 overexpression has been proved to be associated with aggressive behaviour and poor survival in different tumours." (PMID 34117958, 2021). "Although many studies have been performed focusing on the association of FEN1 with tumor progression and drug resistance, the relevant mechanisms are not clear and further investigation is warranted." (PMID 33827468, 2021). "FEN1 blockade in BC induced proteasome-mediated degradation of activated ERα, resulting in loss of ERα-driven gene expression and eradicated tumor cell proliferation." (PMID 34277392, 2021). "As previously discussed, depletion and/or inhibition of FEN1 activity showed more impact risk on tumour cells than in adjacent normal cells, which revealed the poor outcome for patients who had DCIS." (PMID 34117958, 2021). "So, in mouse models, it has been shown that FEN1 deficiency significantly contributes to the frequency and multiplicity of the occurrence of tumours." (PMID 31572192, 2019). "We also observed that the variant rs4246215 genotypes in the FEN1 gene demonstrated a decreased association with tumor size." (PMID 27801669, 2016). "FEN1 has been widely recognized as a tumor suppressor in previous studies, and FEN1 haplo-deficient mice allow the accumulation of replication intermediates leading to genomic instability, which promotes rapid tumor development." (PMID 39759116, 2025). "Hence, the increased dependence of PARG;BRCA2-deficient cells on EXO1/FEN1 function is also relevant in human tumor cells." (PMID 38360994, 2024). "Numerous studies have implicated FEN1 as an effective target for the treatment of tumor resistance." (PMID 35883563, 2022). "Moreover, FEN1 L209P variant expression was prone to induce cellular transformation and tumor growth in a mouse xenograft model." (PMID 34277392, 2021). "High FEN1 mRNA level was associated with younger patient age (p = 0.037), large tumour size (p < 0.001), high nuclear grade (p < 0.001), positive lymph node involvement (p < 0.001), hormonal receptor negativity (p < 0.001), positive HER2 status (p < 0.001) and basal-like subgroup (p < 0.001)." (PMID 34117958, 2021). "FEN1 mutations or insufficient activity degrading apoptotic DNA may lead to chronic inflammation, immune diseases and tumor progression." (PMID 33827468, 2021). "High FEN1 expression is linked to features of aggressive tumour behaviour and may play a role in the direct progression of DCIS to invasive disease." (PMID 34117958, 2021). "Although the correlation between FEN1 expression and tumor progression had been demonstrated, further study was required to clarify whether the overexpression of FEN1 was a cause or a result of tumor progression." (PMID 28371273, 2017). "Homozygous deletion of the RAD27 homolog FEN1 in mice is lethal, but heterozygous deletion in combination with mutation of the adenomatous polyposis coli (Apc) gene results in increased numbers of adenocarcinomas, enhanced tumor progression and decreased survival." (PMID 26545110, 2015). "The expression of FEN1 is often upregulated in various solid tumors, including ovarian, breast, and non-small cell lung cancers, contributing to enhanced tumor progression and chemotherapy resistance." (PMID 40612863, 2025). "In this context, FEN1 acts as a protease that facilitates the repair of damaged DNA, thus playing a critical role in mediating the effects of cisplatin on tumor cells." (PMID 40612863, 2025).
tumor (continued). "As anticipated, EWS cells were more sensitive to FEN1 inhibition than non-EWS cells, confirming EWS cells as an identifiable tumor indication with specific sensitivity to FEN1 inhibition." (PMID 41359388, 2025). "It is a direct target of miR-4324, whose expression is significantly downregulated in OvCa, thereby enabling oncogenic FEN1 activity and tumour growth in vivo." (PMID 41008855, 2025). "FEN1 is overexpressed in OvCa tumours, where it contributes to tumorigenesis by promoting proliferation, migration, colony formation, and reducing cell adhesion." (PMID 41008855, 2025). "This underscores the potential role of FEN1 as a driver of tumor progression in NB, suggesting its importance as a target for therapeutic strategies." (PMID 40612863, 2025). "Compared to FEN1-high tumor cells, FEN1-low tumor cells exhibited increased and stronger communication with surrounding cells." (PMID 38962012, 2024). "Together, our findings strongly suggest FEN1 and EXO1 to be useful as pharmaceutical targets for PARG-deficient tumor cells, as well as for the optimization of PARGi in precision oncology." (PMID 38360994, 2024). "Tumor cells were segregated into FEN1-high and FEN1-low groups based on the median expression of FEN1." (PMID 38962012, 2024). "The enhanced communication between FEN1-low tumor cells and the surrounding cells, as revealed through our analysis, suggests a more dynamic interplay within the TME." (PMID 38962012, 2024). "Alterations in the invasive capacity of NB cells post-FEN1 modulation underscore the gene’s role in tumor metastasis." (PMID 38962012, 2024). "Pseudotime trajectory analysis illustrated the temporal expression changes of FEN1 in the development of NB tumor cells." (PMID 38962012, 2024). "Our study showed that FEN1 was significantly upregulated in HCC and that high FEN1 expression was associated with higher tumor T stage, tumor M stage and tumor stage." (PMID 38230217, 2024). "The observation that FEN1 expression is higher in the early stages of tumor cell development suggests a role in the initial phases of tumorigenesis or in maintaining a stem-like state of the tumor cells." (PMID 38962012, 2024). "The median FEN1 gene expression was extended in tumor tissue and even more in metastatic tissue (p = 6.98 × 10−17)." (PMID 38396787, 2024). "Cell-cell communication analysis further investigated differences between FEN1-high and FEN1-low tumor cells in their interactions with the TME." (PMID 38962012, 2024). "Tumour tissues with FEN1 knockdown showed lower levels of Ki67, while Ki67 expression was statistically significantly increased in tumour tissues with FEN1 overexpression as compared with other mice in the 22Rv1‐Ctrl group." (PMID 37326412, 2023). "Based on the mRNA expression profile of GC tumor and adjacent normal tissues from the GSE13861 and GSE54129 cohorts, FEN1, PDGFRB, SERPINE1, and TCF3 were up-regulated in tumor tissues, which coincide with their risk roles in the senescence-related signature." (PMID 37100457, 2023). "Among the selected genes, only RPA1, MCM5 and FEN1 had significantly (p < 0.05; q < 0.05) higher mRNA expression in BRAFV600E-mutated tumor samples in comparison with unaltered group." (PMID 37106808, 2023). "Flow cytometry results also showed FEN1 knockdown led to increased apoptosis and G1/S phase arrest in tumour cells treated with DTX in vivo, whereas FEN1 overexpression achieved the opposite results." (PMID 37326412, 2023). "The results showed that FEN1 overexpression significantly increased tumor weights compared with the control group." (PMID 37993428, 2023). "Considering the importance of FEN1 in tumour growth, we assessed the effects of FEN1 on Ki67 expression by immunohistochemistry (IHC)." (PMID 37326412, 2023).
tumor (continued). "Conversely, FEN1 overexpression resulted in a statistically significant increase in tumour cell viability compared with the 22Rv1‐Ctrl (78.12 ± 1.34 vs. 54.7 ± 1.89, p < 0.0001) and LNCaP‐Ctrl groups (83.15 ± 2.99 vs. 62.64 ± 2.18, p < 0.0001)." (PMID 37326412, 2023). "This inhibitor was modified by phosphorothioate to slow down FEN1 catalysis and inhibit tumor growth." (PMID 35883563, 2022). "These small molecule inhibitors affect Okazaki fragment maturation, genomic stability or DNA damage repair pathways (BER, HRR) by inhibiting FEN1, then killing tumor cells or increasing tumor sensitivity to chemotherapy drugs." (PMID 35883563, 2022). "Firstly, overexpression of FEN1 was determined in HCC tissues of 50 pairs matched tumor/ adjacent cases." (PMID 35173534, 2022). "Next, 3D spheroid model to further investigate the function of FEN1/USP7 axis in tumor growth and invasion." (PMID 35173534, 2022). "FEN1 is expressed in proliferating cells and is overexpressed in different tumours such as prostate, testis, lung, brain, gastric and breast." (PMID 35883600, 2022). "The dysregulation of FEN1 in various tumors is closely related to tumor development and chemotherapy resistance, and is considered to be a marker of multiple tumor metastasis and poor prognosis." (PMID 35883563, 2022). "FEN1 protects perturbed forks from erroneous over-resection by MRE11 through regulating of BRCA1-RAD51 and WRN helicase, uncovering an essential genetic interaction between FEN1 and DNA-PKcs in mitigating replication-stress induced tumor genomic instability." (PMID 35414100, 2022). "Inhibition of FEN1 can activate the proteasome-mediated degradation of ERα, leading to a decrease in ERα expression and inhibiting the proliferation of tumor cells." (PMID 35883563, 2022). "Our previous study indicated that the overexpression of another key BER pathway enzyme, flap structure-specific endonuclease 1 (FEN1), promoted tumor progression and conferred cisplatin (DDP) resistance in NSCLC8." (PMID 34006852, 2021). "The Oncomine database was used to analyze differences in FEN1 mRNA expression between tumor and normal tissues." (PMID 34277392, 2021). "We verified the increased RNA expression of MMEJ-related H2ax, Fen1, Cdk1, Plk1, and Polθ and decreased RNA expression of Mdc1 in the MmuPV1 tumor tissues by real-time RT-qPCR." (PMID 34343212, 2021). "The connection between FEN1 and tumor burden indicators, including tumor size, node status, and stage was estimated." (PMID 34277392, 2021). "High FEN1 nuclear expression was significantly associated with serous type carcinomas (p = 0.018), higher FIGO stage at presentation (p = 0.005) and higher tumor grade (p = 0.038)." (PMID 33919707, 2021). "Shen BH was the most active author publishing articles on FEN1 and focused mainly on DNA replication, DNA repair and tumor biology." (PMID 33827468, 2021). "This study indicated frontiers of FEN1, which included oxidative stress, phosphorylation and tumor progression and therapy." (PMID 33827468, 2021). "The expression levels of FEN1 were also positively correlated with tumor size (P = 0.047 < 0.05), distant metastasis (P = 0.013 < 0.05) and vascular invasion (P = 0.024 < 0.05) in HCC34." (PMID 33750838, 2021). "The Flap endonuclease (FEN1) expression levels were also positively correlated with tumor size (P = 0.047 < 0.05), distant metastasis (P = 0.013 < 0.05) and vascular invasion (P = 0.024 < 0.05) in HCC." (PMID 33552715, 2021). "Within the irradiated group, we found downregulation of UNG, FEN1, PARP3, POLD, NTLH1, ERCC1 and MPG which are linked to increased DSBs, sensitivity to alkylating agents, impaired tumor growth and reduced EMT, DSB repair and mitotic progression." (PMID 34680264, 2021). "In recent years, the research of FEN1 in oncology has increased, which has promoted the understanding of tumor occurrence, development, prevention and treatment." (PMID 33827468, 2021).
tumor (continued). "FEN1 high expression in DCIS was associated with aggressive and high-risk features including higher nuclear grade, larger tumour size, comedo type necrosis, hormonal receptors negativity, higher proliferation index and triple-negative phenotype." (PMID 34117958, 2021). "Decreased FEN1 level was also observed in post-operative patients, suggesting that it can be used to monitor tumor progression and predict the prognosis of BC patients." (PMID 34277392, 2021). "A study on HCC revealed that lower doses of cisplatin activate the DNA repair capability of FEN-1, which leads to cisplatin resistance, whereas high doses of cisplatin activate the endonuclease activity of FEN-1, resulting in apoptotic death of tumor cells." (PMID 34358082, 2021). "The abnormal expression of FEN1 in tumor cells is connected with the undermethylation of CpG islands in the FEN1 promoter region." (PMID 33827468, 2021). "Overall, we found a positive correlation between high expression of FEN1 in tumor tissues and the late TNM stage." (PMID 32399086, 2020). "In non-small-cell lung carcinoma (NSCLC), FEN1 inhibition can promote apoptosis of tumor cells, in turn leading to higher sensitivity to cisplatin." (PMID 32318339, 2020). "High FEN1 expression is often a common feature of active replication cells, which is consistent with the fact that tumor cells, due to their vigorous growth speed, have a higher FEN1 expression than normal cells." (PMID 32586310, 2020). "A comparison between diseases and healthy tissues showed that expression of FEN1 mRNAs was universally upregulated in most tumor tissues, including HCC (P < 0.001)." (PMID 32399086, 2020). "Meanwhile, some reports also pointed that FEN1 expression influence on tumor cell growth to anticancer drugs, it can accelerate tumor cell growth and confers cisplatin resistance in NSCLC." (PMID 32340320, 2020). "CRISPR technology was used to knockdown FEN1 expression level of 293T cells, and tumor xenograft in nude mice was employed to determine the effects of FEN1 inhibitor and IR exposure on tumor growth in vivo." (PMID 31670906, 2019). "PCNA and FEN1 expression were significantly above tumor average in subtype 2, as were EXO1 and LIG1." (PMID 31857847, 2019). "FEN1 levels were also positively correlated with tumor size, distant metastasis and vascular invasion." (PMID 31534853, 2019). "IHC stained tumor tissue sections displayed lower FEN1 expression in the Sh3-FEN1 group and higher FEN1 expression in the OE-FEN1 group compared to the corresponding control groups." (PMID 31402791, 2019). "There were significant correlations between FEN1 expression and tumor size (P = 0.047 < 0.05), metastasis (P = 0.013 < 0.05) and vascular invasion (P = 0.024 < 0.05)." (PMID 31534853, 2019). "FEN1, which is a key player in DNA replication, repair as well as alleviating the replication stress, is important for tumor growth." (PMID 31824839, 2019). "RT-qPCR analysis in 21 pairs of matched HCC tissue and para-tumor tissue samples consistently showed a higher FEN1 mRNA expression in HCC tissues." (PMID 31402791, 2019). "Using a tumor mouse model, we showed that the inhibition of FEN1 impeded the progression of tumor growth by activating intrinsic pathway of apoptosis, thereby enhancing the animal's lifespan." (PMID 28371273, 2017). "To further investigate the impact of FEN1 inhibition on tumor progression in vivo, we used nude mice to do a xenograft study." (PMID 28371273, 2017). "After the tumor volume reached 100–200 mm3, mice were treated with the FEN1 inhibitor, cisplatin, or the combination of the FEN1 inhibitor and cisplatin." (PMID 28371273, 2017). "In mouse model, haploinsufficiency of FEN1 leads to rapid tumor progression with increased numbers of adenocarcinoma and decreased survival." (PMID 26431531, 2015). "After excluding cases with insufficient tumor tissue in tissue micro-array, FEN1 expression was detectable in 268 cases, and YY1 expression was detectable in 285 cases." (PMID 25885449, 2015).
tumor (continued). "We first targeted the interaction between FEN1 and CDC4, owing to the fact that CDC4 has been shown to be a CIN gene mutated in many tumor types." (PMID 23382697, 2013). "In addition to miR-4324, miR-134-3p has also been reported to exert tumour-suppressive effects by directly targeting FEN1." (PMID 41008855, 2025). "FEN1 could serve as a tumor marker to detect patients with a high probability of progression and to predict the outcome." (PMID 38396787, 2024). "Enhanced invasiveness in FEN1 OE cells could reflect an increased ability to facilitate tumor spread." (PMID 38962012, 2024). "Furthermore, pseudotime trajectory analysis elucidating the temporal changes in FEN1 expression across the developmental trajectory of NB tumor cells underscores its significance." (PMID 38962012, 2024). "However, similar to the results for tumour volume, FEN1 overexpression reversed the decreased expression of Ki67caused by AR knockdown." (PMID 37326412, 2023). "Although flap endonuclease-1 (FEN1), a pivotal DNA-related enzyme is involved in DNA base excision repair to maintain the stability of the cell genome, the correlation between FEN1 and tumor immunity has been unexplored." (PMID 37185662, 2023). "Accumulating evidence indicates that FEN1 is necessary for tumour progression." (PMID 37326412, 2023). "In addition, tumour volume and tumour/body weight index were statistically significantly increased in the 22Rv1‐si‐AR+FEN1‐OE group as compared with the 22Rv1‐control and 22Rv1‐AR‐KD groups (both p < 0.0001)." (PMID 37326412, 2023). "FEN1 is a structure‐specific endonuclease that participates in DNA repair and contributes to tumour progression, metastasis and drug resistance in a variety of tumour types." (PMID 37326412, 2023). "FEN1 inhibitor-based four chemical structure N-hydroxy urea compounds (Compound #2, Compound #8, Compound #16 and Compound #20) had significant effects on several tumor models, according to previous reports." (PMID 35883563, 2022). "It is reasonable that FEN1 might enhance the malignant behaviors through activate or inactivate tumor-promotors or tumor-suppressors." (PMID 35173534, 2022). "FEN1 haploinsufficiency can promote tumor progression and higher FEN1 expression may result in reduced risk of malignant transformation in gastrointestinal cells." (PMID 33827468, 2021). "Functional insufficiency of FEN1 haplotypes promote tumor progression." (PMID 33827468, 2021). "In tumour cells, down regulation of FEN1 protein could enhance DNA-damaged inducing agent’s toxicity leading to both DNA replication and repair failure." (PMID 34117958, 2021). "However, later studies have shown roles of FEN1 in the initiation and promotion of tumor progression." (PMID 33827468, 2021). "Our results showed that FEN1 inhibition could improve the anti-tumor effect of ROS inducer ATO by promoting ROS accumulation and reduce the application concentration of ATO." (PMID 32318339, 2020). "All these results above indicated that the inhibition of FEN1 could enhance the anti-tumor effect of ATO, both in vitro and in vivo." (PMID 32318339, 2020). "Numerous studies have described the role played by FEN1 in tumor formation and proliferation." (PMID 32399086, 2020). "For example, FEN1 functions in multiple pathways of DNA metabolism and promotes tumor progression." (PMID 33193623, 2020). "FEN1 promotes tumor progression, proliferation and poor prognosis of NSCLC." (PMID 31867044, 2019). "In the development of tumours, FEN1 plays the role of an oncogene." (PMID 31572192, 2019). "Negative regulation of LINC00152 and FEN1 by YY1 leads to tumor suppression." (PMID 31824839, 2019). "Moreover, the expression of FEN1 in HCC was higher than that of non-tumor tissues according to the GEPIA database." (PMID 31402791, 2019). "This indicates FEN1 expression influence on tumor cell growth to anticancer drugs." (PMID 28187440, 2017).